CCL18 (C-C motif chemokine ligand 18)
Diseases named in the same sentence as CCL18 in open-access papers (continued):
Sharing a sentence is not in itself a finding about the gene and the disease.
urinary tract infection (1 paper, 2012). "The specificity of promising biomarkers such as CCL18 needs to be tested in cohorts that are known to be problematic with other urine-based assays (e.g., hematuria, urinary tract infection, stones and voiding dysfunction)." (PMID 22629457, 2012).
uveitis (1 paper, 2020). An inflammatory process affecting a part of or the entire uvea. "Supporting our observation that the mRNA for CCL18 is increased, CCL18 has been reported in uveitis in human samples of aqueous humor in 12/30 samples." (PMID 31877281, 2020).
Vestibular schwannoma (1 paper, 2024). A vestibular schwannoma (also known as acoustic neuroma, acoustic neurinoma, or acoustic neurilemoma) is a benign, usually slow-growing tumor that develops from the VIIIth cranial nerve supplying the inner ear. "In addition to CCL2, the examination of our cell culture supernatants of VS primary cultures suggests that vestibular schwannoma cells produce the cytokines CCL5, CCL18, TGFB1, and GDF15, which has not yet been investigated for VSs." (PMID 39272860, 2024).
viral infection (1 paper, 2020). "Moreover, CCL18 from ISG15-treated TAMs may establish a loop between viral infection, TAMs and tumor progression." (PMID 33424843, 2020).
ZIKV infection (1 paper, 2022). "The downregulation of inflammatory genes CCL18, CCL19, CXCL6, CXCL9, IL6R, IL11, IL24, and Integrin Subunit Beta 3 (ITGB3) with ZIKV infection may reflect placental immune tolerance." (PMID 35304593, 2022).
tumor (299 papers, 2010 to 2026). "In terms of tumor-associated macrophage (TAM), CCL18 produced by M2-like TAMs can induce epithelial–mesenchymal transition, enhance the stemness of tumor cells, and promote tumor metastasis." (PMID 39085744, 2025). "CCL18 also influences DC fate by attracting immature DCs to the tumour niche, where they differentiate into tumour-associated DCs (TADCs), which produce immunosuppressive IL-10 and indoleamine 2,3-dioxygenase (IDO), further expanding Tregs." (PMID 40361472, 2025). "CCL18 derived from tumor-associated macrophages (TAMs) plays a critical role in promoting BRCA metastasis via its receptor, PITPNM3." (PMID 40692603, 2025). "Treg-associated chemokine receptor CCR8 ligands, CCL8, CCL16 and CCL18, were also elevated in tumour tissue stellate, epithelial and endothelial cells." (PMID 39915477, 2025). "These SPP1+CCL18+ TAMs are associated with increased tumor growth and metastasis, primarily due to their high expression levels in metastasis-associated and EMT pathways." (PMID 39286635, 2024). "CCL18 is a chemokine secreted by tumor-associated macrophages that promotes a pro-tumor microenvironment by inducing a pro-tumor (M2-like) macrophage phenotype." (PMID 38730286, 2024). "C-C motif chemokine 18 (CCL18), that is M2-tumor-associated macrophages, regulates post-translational modifications in A549 cells via PPP." (PMID 38841622, 2024). "CCL18 (C-C Motif Chemokine Ligand 18), Tumor-associated macrophages (TAMs) are vital in the malignant tumors’ development." (PMID 37434120, 2023). "CCL18 is secreted by tumour-associated macrophages and was associated with cancer progression in other cancer types." (PMID 37965317, 2023). "In other cancers, the chemokine CCL15 has been linked to tumor-associated macrophage recruitment and CCL18 has been linked to an immunosuppressive tumor microenvironment, allowing for evasion of the host’s immune system." (PMID 37895248, 2023). "We then designed and screened a blocking peptide targeting Chemokine C–C motif ligand 18 (CCL18) derived from tumor associated macrophages and validated its potency by MTT assay." (PMID 36850011, 2023). "Another component of the TME in BC is tumor-associated macrophages (TAMs), which promote angiogenesis and tumor progression via releasing a proangiogenic factor, CCL18." (PMID 35203510, 2022). "CCL18 is predominantly secreted by M2 tumor-associated macrophages but is also expressed in other immune cells, such as monocytes and dendritic cells." (PMID 35159163, 2022). "Previous studies have demonstrated that CCL18 released by tumor-associated macrophages induced EndMT in endothelial cells, altering HUVEC morphology, suppressing VE-cadherin expression and increasing the levels of vimentin and fibronectin." (PMID 35159163, 2022). "The chemokine (C-C motif) ligand 18 (CCL18) plays an important role in the progression of cancers, and this chemokine is mainly produced by tumor-associated macrophages (TAMs)." (PMID 35059433, 2021). "CCL18 is associated with a poor prognosis in solid tumors, but this is rather related to its role in tumor angiogenesis than a role in Treg recruitment." (PMID 33924428, 2021). "Previous studies have found that CCL18 is up-regulated in malignant tumors, and can promote the invasion and metastasis of tumor cells, which is a potential pathogenic molecule of urothelial carcinoma." (PMID 35059433, 2021). "CCL18, mainly secreted by tumor-associated macrophages (TAMs) in tumors, was positively correlated with malignancy in EC." (PMID 33869285, 2021). "And CCL18 is associated with recruitment of tumor-associated macrophages (TAMs), Treg, tumor-associated dendritic cells (TADCs), and cancer-associated fibroblast (CAFs)." (PMID 33648605, 2021). "Beyond its pro-angiogenic activity, CCL18 can also promote endothelial to mesenchymal transition (EndMT) in the tumor microvasculature, which can lead to loss of cell-to-cell junctions, and enhanced invasion and migration." (PMID 34926282, 2021).
tumor (continued). "CCL18 is a C-C chemokine mainly secreted by M2 type tumor associated macrophages which acts mainly by binding to its corresponding chemokine receptor CCR8." (PMID 33795528, 2021). "Although the interplay between M2 macrophages and tumor cells is a complicated mechanism involving various factors, these results suggested that CCL18 secreted by M2 macrophages was one of the factors associated with the interaction." (PMID 33052231, 2020). "The presence of CCL18 was associated with the subsequent increased recruitment of Tregs in the tumor, peritoneal cavity and peripheral blood." (PMID 33353113, 2020). "This chemokine is a marker of the M2 macrophage subset; this is the reason why an increase in the production of CCL18 is associated with the immunosuppressive nature of the tumor microenvironment and an important element of cancer immune evasion." (PMID 33114763, 2020). "For this reason, CCL18 is essential in the interdependence of TAMs and CAFs, as well as in the influence of these cells on regulatory T cells (Treg) and tumor-associated dendritic cells (TADCs)." (PMID 33114763, 2020). "The high concentration of CCL18 in the neoplastic tumor causes the displacement of GAG-bound chemokines, which disrupts their functioning." (PMID 33114763, 2020). "Taking into consideration 17 types of neoplasms, only in 4 cases an increased level of CCL18 is associated with a worse prognosis for patients, and in other 4, with a better one." (PMID 33114763, 2020). "CCL18 is a cytokine secreted by M2 type tumor associated macrophages, which frequently over-expressed in diverse human cancers." (PMID 31839826, 2019). "Our previous study showed that chemokine (C‐C motif) ligand 18 (CCL18), derived from tumour‐associated macrophages (TAMs), regulates SCCHN metastasis by promoting epithelial‐mesenchymal transition (EMT) and preserving stemness." (PMID 30768878, 2019). "Although this study, however, described expression by tumor cells, a previous report concluded that CCL18 was selectively expressed by tumor-associated host cells with macrophage morphology." (PMID 29141914, 2018). "In summary, increased chemokine ligand CCL18, predominantly produced by cancer epithelial cells, is associated with advanced tumor stage in OSCC." (PMID 26919103, 2016). "We also identified a positive association between CCL18 expression and tumor TNM stage in OSCC patients (P = 0.040)." (PMID 26919103, 2016). "This was in agreement with a study that showed M2-type chemokine CCL18 was expressed in a subset of tumor-infiltrating Mφs and that its level was associated with prolonged survival in GC patients." (PMID 26840565, 2016). "Remodeling of the tumor stroma can also occur through the production of CCL18 from tumor-associated macrophages, which accelerates the invasive properties of breast cancer." (PMID 22482060, 2012). "Additionally, the immunosuppressive chemokine CCL18 is highly abundant in OC patients and elevated levels of CCL18 facilitate tumor migration, metastasis, and are inversely associated with overall survival (OS)." (PMID 40369674, 2025). "Besides other consequences, higher concentrations of CCL18 in the serum or the tumor are linked to a worse prognosis for cancer patients." (PMID 40692603, 2025). "CCL18 helps recruit naive T cells and Tregs and, in a fashion analogous to CCL18+ tumor-associated macrophages (TAMs) in cancer, may promote a regulatory environment." (PMID 40371647, 2025). "Soluble pro‐inflammatory factors such as CCL2, CCL5, and CCL18 secreted by TAMs from the primary tumor have been implicated in the formation of a pre‐metastatic niche in distant organs such as the lungs and the bones, increasing tumor cell colonization." (PMID 38426622, 2024). "TME deconvolution and cell interaction analyses allow us to identify the chemokine CCL18 secreted by tumor associated macrophages could promote tumor cell proliferation via JAK2/STAT3 signaling pathway and lead to poor prognosis of ESCC." (PMID 36850011, 2023).
tumor (continued). "C‐C Motif Chemokine Ligand 18 (CCL18) is mainly produced by tumor‐associated macrophages, which may be associated with tumor cell migration." (PMID 34995016, 2022). "Notably, the upregulation of CSF1 and CCL18—as identified in the TME of ALK-positive tumors —increases type 2 (M2) tumor-associated macrophages (TAM) which have tumorigenic functions and are known to contribute to immune evasion." (PMID 34125345, 2022). "Previous studies have shown that CCL18 overexpression may be associated with tumor growth and development, especially in the tumor microenvironment, and it is considered a useful marker for diagnosis and prognosis." (PMID 34995016, 2022). "CCL18 expression in blood or tumor stroma was also associated with metastasis and reduced survival." (PMID 34503058, 2021). "NEFM transcriptional expression was negatively associated with CCL7, CCL8 and CCL18, which would recruit monocytes to differentiate into tumor-associated macrophages (TAMs) at the tumor site, indicating that NEFM may cause decreased M2 macrophage infiltration." (PMID 34001208, 2021). "CCL18 (C-C Motif Chemokine Ligand 18) is a chemokine involved in migration and activation of leucocytes; it is overexpressed in several cancer tissues, including GC, and is associated with tumor metastasis, as recently reviewed." (PMID 32117120, 2020). "In addition, the expression of CCL18 in tumor cells is also associated with enhanced invasion and migration." (PMID 33224886, 2020). "Lin and her colleague have found that CCL18 released by tumor‐associated macrophages (TAMs) could promote angiogenesis and tumor progression in breast cancer." (PMID 32253815, 2020). "CCL18 causes the chemotaxis of immature DCs into the tumor niche." (PMID 33114763, 2020). "The activation of this receptor by CCL18 also causes the migration of tumor cells." (PMID 33114763, 2020). "The paper also describes the effect of CCL18 on the recruitment to the cancer niche and the functioning of cells such as TAMs, regulatory T cells (Treg), cancer-associated fibroblasts (CAFs) and tumor-associated dendritic cells (TADCs)." (PMID 33114763, 2020). "In addition, the progression of PDAC can be promoted by tumor associated macrophages by promoting the Warburg effect through CCL18/NF-kB/VCAM-1 pathway." (PMID 33489882, 2020). "CCL18 also causes the chemotaxis of immature DCs, which shows that this chemokine may be involved in the direct recruitment of immature DCs into the tumor niche." (PMID 33114763, 2020). "Furthermore CCL18 is elevated in several malignancies as it is produced by tumor associated macrophages." (PMID 28957436, 2017). "Moreover, lenti-miR98 infection abrogated the weight loss and prolonged the survival of tumor bearing mice treated with CCL18." (PMID 26244871, 2015). "Thus, CCL18 is not only a mediator released by tumor-associated macrophages and potentially reflecting the tumor size but it also influences neoplastic processes of adenocarcinoma." (PMID 23349697, 2013). "Collectively, skewed immune cells such as TAM and Treg, special angiogenic vessels such as tumor-associated endothelial cells, and various proinflammatory cytokines/chemokines including CCL18 and CCL22 are synergistically involved in the suppression of anti-tumor immunity." (PMID 24213462, 2012). "In addition, oncogenic Kras driven metabolic reprogramming in pancreas cancer cells utilizes cytokines from tumour microenvironment, and tumour‐associated macrophages in tumour microenvironment promote progression and the Warburg effect via the CCL18/NF‐kB/VCAM‐1 pathway in PDAC." (PMID 33942483, 2021). "Comparative tumor analysis of CCL18 expression in GEPIA 2 (GEPIA 2) demonstrated significantly elevated expression levels in DLBCL relative to other malignant tumor types." (PMID 41472741, 2025).
tumor (continued). "These interactions primarily suggest CCL18's involvement in immune response and chemotaxis, particularly in the context of macrophage and T cell recruitment to tumor sites, which correlates with its previously discussed role in BRCA progression." (PMID 40692603, 2025). "TAMs secrete pro-EMT factors such as TGF-β and CCL18, which induce mesenchymal transition in neighboring tumor cells." (PMID 40835684, 2025). "Lactate can promote lactoylation of lysine 18th position of histone H3 and activate CCL18 expression through macrophage Gpr132-mediated signaling pathway, while inducing polarization of M2 phenotype, which in turn promotes tumor proliferation and metastasis." (PMID 40703527, 2025). "CCL18 also promotes tumor growth and metastasis by inducing epithelial–mesenchymal transition through the PI3K/Akt/GSK3/Snail signaling pathway." (PMID 40692603, 2025). "These macrophages subsequently release CCL18, a promiscuous chemokine known to drive tumor progression and metastasis." (PMID 39911389, 2025). "CCL18, predominantly expressed by tumor-associated macrophages, has been shown to promote epithelial-to-mesenchymal transition (EMT), tumor cell migration, and invasion." (PMID 40835683, 2025). "M2d macrophages secrete VEGF, IL-10, and CCL18, contributing to tumor progression by promoting angiogenesis and suppressing T cell proliferation, thereby facilitating immune evasion and tumor growth." (PMID 40055311, 2025). "In various cancers, including colon and renal carcinoma, CCL18 expression is enhanced by the β-catenin pathway, highlighting its role in the tumour adaptive response." (PMID 40361472, 2025). "The transition reduces phagocytosis, impairs immune responses, and increases the release of the tumor‐promoting chemokine CCL18, reprogramming macrophage function and creating an immunosuppressive microenvironment." (PMID 40552574, 2025). "CCL18+ TAMs are identified as terminally differentiated macrophages with potent immunosuppressive capabilities; the CCL18 they secrete can directly inhibit T cell function and enhance tumor metastatic potential." (PMID 41459510, 2025). "We noted that only CCL18 expression was significantly upregulated in tumour tissues compared with normal tissues." (PMID 37935468, 2024). "CCL18 serves as an indicator of the M2 macrophage subset, contributing to the immunosuppressive characteristics of the tumour microenvironment and playing a crucial role in cancer immune evasion." (PMID 38999951, 2024). "The direct chemotactic effect of CCL18 on Treg cells and its role in modulating the immunosuppressive tumor microenvironment are well-established." (PMID 38511143, 2024). "In HNSCC, TAMs expressing SPP1 give rise to a pro-angiogenic SPP1+CCL18+ TAM subset, implicated in tumor growth and metastasis." (PMID 39286635, 2024). "CCL18+ TAMs function through signaling pathways involving CCL18 mRNA expression, which promotes tumor metastasis by interacting with receptors like PITPNM3 on tumor cells." (PMID 39457004, 2024). "As a result, higher levels of CCL18 in both the bloodstream and the tumour are correlated with a poorer prognosis for the patient." (PMID 38999951, 2024). "ACKR1 on the surface of endothelial cells binds, clears and regulates various chemokines such as CXCL1, CXCL2, CCL13 and CCL18, which play key roles in angiogenesis and tumour progression." (PMID 39601163, 2024). "CCL18 is involved in tumor invasion, migration, epithelial-to-mesenchymal transition (EMT), and angiogenesis, ultimately contributing to cancer progression." (PMID 38730286, 2024). "CCL18 has been found to play a role in tumour cell proliferation, although its effects seem to vary depending on the type of tumour." (PMID 38520216, 2024). "Further examination of gene expression profiles from 84 ESCC tumors identified that the chemokine CCL18 promotes tumor cell proliferation through the JAK2/STAT3 signaling pathway." (PMID 39415846, 2024).